CD68 (CD68 molecule)
Diseases named in the same sentence as CD68 in open-access papers (continued):
Sharing a sentence is not in itself a finding about the gene and the disease.
acute appendicitis (2 papers, 2019 to 2024). "Pathology identified appendicitis and serosal involvement of GIST in all specimens staining positive for CD68, CD117, and vimentin." (PMID 30918739, 2019). "The increase in the number of CD68-positive cells and CD163-positive cells (macrophages) in both groups with acute appendicitis may indicate containment of the infectious agent or an undesirable effect of an inflammatory reaction based on immune system dysregulation." (PMID 38397914, 2024). "Additionally, the number of CD68-positive macrophages was significantly increased in children with acute appendicitis without COVID-19 infection." (PMID 38397914, 2024).
acute pancreatitis (2 papers, 2012 to 2022). An acute inflammatory process that leads to necrosis of the pancreatic parenchyma. "This study suggests a role for F4/80− CD68+ macrophages in the pathogenesis of acute lung injury in acute pancreatitis." (PMID 23110041, 2012). "Our data showed an enriched population of CD68+CCR2+ and CD68+CD206+ macrophages in the lungs in animals with acute pancreatitis." (PMID 23110041, 2012). "The increase in the CD68+CCR2+ population in the acute pancreatitis group at 24 hours favors the recruitment of these cells via CCL2/CCR2 axis into the lungs." (PMID 23110041, 2012). "Considering the increased levels of the CCL2 in the lung tissue of the acute pancreatitis groups and the immunohistochemistry data for F4/80 antigen, the macrophage populations in the lungs were further analyzed by adding another cell marker (CD68)." (PMID 23110041, 2012).
alcoholism (2 papers, 2017 to 2021). "To evaluate the synergistic relationship between alcoholism and HHV-6, we next evaluated their combined effects on microglia (CD68, CD11b and Iba1)." (PMID 34572401, 2021).
Allergy (2 papers, 2016 to 2022). An allergy is an immune response or reaction to substances that are usually not harmful. "In parallel, also the numbers of Iba1+MHCII+ cells (control: 8433 ± 919 cells/mm3, allergy: 9829 ± 915 cells/mm3; p < 0.0060) and of Iba1+CD68+ cells (control: 9370 ± 638 cells/mm3, allergy 10676 ± 1123 cells/mm3; p < 0.0098) increased." (PMID 27445696, 2016). "However, the number of microglia expressing CD68, a widely used marker for microglial activation, which is located in phagosomes and lysosomes, was unaffected, suggesting that allergy affects predominantly antigen presentation." (PMID 27445696, 2016). "While significantly fewer Iba1+ cells also expressed MHCII in allergic mice (control: 7172 ± 913 cells/mm3, allergy: 5555 ± 766 cells/mm3; p < 0.0001), there was no change in the numbers of Iba1+CD68+ cells (control: 10103 ± 609 cells/mm3, allergy: 10300 ± 1002 cells/mm3; p < 0.6345)." (PMID 27445696, 2016). "Moreover, in our allergy model, the deactivation of microglia seemed to be specific for the hippocampal dentate gyrus, since we actually observed an activation of microglia accompanied by upregulation of MHCII and CD68 in the OB." (PMID 27445696, 2016).
ANCA-associated vasculitis (2 papers, 2019 to 2024). "In vivo, a histological study on kidney biopsies from patients with ANCA‐associated vasculitis reported the presence of METs (identified as MPO+CD68+elastase− macrophages co‐expressing CitH3) in glomerular MPO‐containing macrophages." (PMID 30506885, 2019).
angiomyolipoma (2 papers, 2017 to 2023). A neoplasm with perivascular epithelioid cell differentiation often associated with tuberous sclerosis. "We noticed the characteristic co-expression of melanocytic (HMB-45, Melan A), histiocytic (CD68), and smooth muscle (SMA) markers (data not shown), which supports the unique nature of angiomyolipoma as a tumor with the ability for different phenotypic and immunotypic presentations." (PMID 29308833, 2017).
anthracosis (2 papers, 2013 to 2025). A chronic lung disorder characterized by deposition of coal dust in the lung parenchyma leading to the formation of black nodules and emphysema. "We assessed the prognostic value of anthracosis intensity, CD68+ myeloid cluster infiltration associated with anthracosis and pSTAT3 level." (PMID 23717691, 2013). "CD68+ myeloid clusters associated with anthracosis and with an immunosuppressive and metastasis-promoting phenotype and elevated overall STAT3 activity were observed in uninvolved lymph nodes." (PMID 23717691, 2013). "We characterized the phenotype of CD68+ myeloid clusters associated with anthracosis in uninvolved regional LNs from NSCLC patients with smoking history with IHC." (PMID 23717691, 2013). "However, CD68+ myeloid cluster infiltration positively correlated with anthracosis intensity and overall pSTAT3 activity." (PMID 23717691, 2013). "In all nodes, the medullary sinus was filled with CD68‐positive and CD169‐negative macrophages, most of which showed anthracosis." (PMID 40151162, 2025).
astrocytic tumor (2 papers, 2015 to 2023). A glial tumor of the brain or spinal cord showing astrocytic differentiation. "In original tumor material, with double immunofluorescence we confirmed that receptor expression occurred in GFAP-positive astrocytic tumor cells as well as on CD68/CD163-positive microglia/macrophages." (PMID 25894595, 2015).
Atrophy (2 papers, 2020 to 2025). Any weakening or degeneration, especially through lack of use. "Based on this classification, patients with higher levels of glomerular CD68+ more commonly had severe interstitial fibrosis/tubular atrophy (p = 0.030), higher median number of interstitial CD68+ cells (p = 0.007), and higher median number of CD163+ cells in the glomerulus (p = 0.019)." (PMID 40338344, 2025). "However, in a case described by Nanri with cerebellar atrophy, Purkinje cell loss and mild Bergmann gliosis, no lymphocytic infiltration was observed (CD3-, CD4-, CD8-, CD20-, CD68-, CD79A-)." (PMID 32244870, 2020).
autoimmune hepatitis (2 papers, 2023 to 2024). Hepatitis caused by autoantibodies. "F4/80+/CD68+ represents macrophages with phagocytic capacity, and our previous study found that depletion of liver macrophages by gadolinium chloride (GdCl3) alleviated liver iron accumulation in autoimmune hepatitis." (PMID 37941054, 2023). "In mice with autoimmune hepatitis (AIH), the inhibition of NLRP3 inflammasome-mediated pyroptosis-derived IL-1β led to a decreased accumulation of CD68-positive cells and CD11b-positive cells in liver tissue." (PMID 38380334, 2024).
B-cell lymphoma (2 papers, 2014 to 2019). "Staining with various immunohistochemical markers revealed that the infiltrating lymphocyte cells were positive for predominance of CD20, while CD68+ cells within the infiltration, which is consistent with B-cell lymphoma." (PMID 24733356, 2014).
bacterial pneumonia (2 papers, 2012 to 2023). Acute infection of the lung parenchyma caused by bacteria (e.g., Streptococcus pneumoniae, Haemophilus influenzae, Chlamydia pneumoniae, Mycoplasma pneumoniae, and Legionella pneumophila). "As concerns inflammatory cells, massive neutrophils infiltration was found in areas affected by bacterial pneumonia (four vaccinated patients, and one unvaccinated patient), while macrophages (CD68+) and lymphocytes (CD3+) were always observed." (PMID 36831087, 2023). "BPIFB1 was localized in CF lung samples along with BPIFA1, MUC5AC, CD68 and NE and directly compared to histologically normal lung tissues and that of bacterial pneumonia." (PMID 22767025, 2012).
calcification (2 papers, 2014 to 2023). Process by which organic tissue becomes hardened by the physiologic deposit of calcium salts. "Arterial calcification has previously been associated with the presence of osteoclasts and, more recently, Bas and colleagues have suggested an active process of mineral resorption that is mediated by CD68+ cells in a rat model for medial artery calcification." (PMID 24906371, 2014). "Similarly, microglia enveloping calcium nodules in the animal model of primary familial brain calcification displayed characteristics of activated microglia, showing upregulation of genes, such as Cd68 and Clec7a, and enrichment of inflammatory pathway genes." (PMID 38188667, 2023).
carotid atherosclerosis (2 papers, 2023 to 2024). A thickening and loss of elasticity of the walls of carotid arteries that occur with formation of atherosclerotic plaques. "The results revealed the co-localization of KMO within CD68-positive macrophages, consistent with the findings derived from our study utilizing WGCNA, machine learning, and immune cell infiltration analysis on a publicly available dataset of human carotid atherosclerosis." (PMID 39026250, 2024).
celiac disease (2 papers, 2019 to 2024). An autoimmune genetic disorder with an unknown pattern of inheritance that primarily affects the digestive tract. "On the other hand, ICI-CD has more CD68+ and PD-L+ macrophages in the lamina propria compared to classic celiac disease." (PMID 39727645, 2024). "Different from celiac disease, ATI elicit a modest immune response in the gut, with a mild increase in CD68+ macrophages and a modest increase of lamina propria dendritic cells/macrophages expressing CD86 and MHC class II, as also confirmed in the present report." (PMID 31767938, 2019).
cerebral malaria (2 papers, 2021 to 2024). A sequestration of Plasmodium falciparum in the brain, which can cause coma and/or seizures. "Also, using an anti-CD68 antibody, there was no immunopositive cell in the brain to attribute the observed effects to cerebral malaria." (PMID 33567845, 2021).
cervical squamous cell carcinoma (2 papers, 2021 to 2024). A squamous cell carcinoma arising from the cervical epithelium. "A similar progression across clinical stages as that observed in PSCC, with increasing density of CD68+ and decreasing CD8+ cells from localized tumors to nodal metastases, was reported in cervical squamous cell carcinoma." (PMID 38275860, 2024).
cholesteatoma (2 papers, 2022 to 2025). A pathologic process characterized by the proliferation of keratinizing squamous epithelium resulting in the accumulation of keratin and cells in the middle ear and/or mastoid. "In the present study, human cholesteatoma specimens acquired during tympanomastoidectomy were retrospectively retrieved and immunohistochemically characterized using a combination of antibodies labeling M1 macrophages (CD80), M2 macrophages (CD163), and total macrophages (CD68)." (PMID 36013064, 2022).
chronic gastritis (2 papers, 2021 to 2024). Inflammation of the stomach that is chronic in nature. "mIHC revealed that FOLR2+ macrophages (CD68+FOLR2+) were enriched in nonatrophic chronic gastritis (NAG) and CIM." (PMID 39702278, 2024).
co-infection (2 papers, 2022 to 2024). "Further investigation of CD4+ T cell and CD68+ macrophage reconstitution within lung tissue was of interest as it is the site of initial infection for Mtb as well as co-localization during co-infection for HIV." (PMID 36146734, 2022).
colon adenoma (2 papers, 2012 to 2020). An adenoma that arises from the colon. "We found that miR-21 expression is associated with high NOS2 and CD68 expression in UC and CD, as well as colon adenomas." (PMID 22970173, 2012). "As in our CRC cohort, PTGS2-positive stromal populations with a luminal distribution were previously observed in colon adenomas: Chapple and Bamba independently attributed PTGS2 positivity to macrophages, according to cell morphology or CD68 expression." (PMID 32168749, 2020).
colorectal adenocarcinoma (2 papers, 2022 to 2023). The most common type of colorectal carcinoma. "In another study, the proinflammatory markers CD68, CD15, IL-6, and TLR4 were upregulated in colorectal adenocarcinoma compared to normal mucosa or premalignant conditions." (PMID 36649244, 2023). "The immunohistochemical sections of colorectal adenocarcinoma from 10 patients (5 from the NED group and 5 from the non-NED group) showed that tumor-associated macrophages (stained by CD68) accumulated where CgA protein was expressed." (PMID 36030223, 2022).
embryonal sarcoma (2 papers, 2022 to 2023). "UESLs are usually diffusely positive for vimentin and a1-antitrypsin and focally positive for cytokeratin, desmin, α-SMA, muscle-specific actin, CD68, myoglobin, neuron-specific enolase, S100, and CD34, suggesting that an embryonal sarcoma is undifferentiated." (PMID 36107353, 2022).
Emphysema (2 papers, 2005 to 2007). "Emphysema patients had an increased number of ICI (CD20, CD3, CD8, CD68, CD45RO, CD4 and PMN) as compared with controls (p ≤ 0.01)." (PMID 15705190, 2005).
Encephalopathy (2 papers, 2017 to 2025). Encephalopathy is a term that means brain disease, damage, or malfunction. "CD68 expression revealed significant differences (p < 0.001) between the encephalopathy group and both control groups." (PMID 28072884, 2017). "Results show, that there were more HHV-6 and CD68 positive cells in the encephalopathy group than the controls." (PMID 28072884, 2017). "There were significantly (p < 0.001) more CD68 positive activated microglial cells in the PCR+ encephalopathy group when compared to the PCR- encephalopathy group as well as both PCR+ control groups." (PMID 28072884, 2017). "The pattern of CD68 positive cells in the encephalopathy group was diffuse with some clustering, whereas in both control groups they were mostly found near capillaries." (PMID 28072884, 2017). "There were more HHV-6 positive oligodendrocytes in the white matter in the PCR+ encephalopathy further strengthening the association among the HHV-6 presence and increased number of CD68 positive cells." (PMID 28072884, 2017). "Furthermore, when only HHV-6 PCR+ encephalopathy cases were studied, we observed similar but stronger associations between HHV-6 positive oligodendrocytes and CD68 positive cells in the white matter." (PMID 28072884, 2017). "Overall, the comparisons between only the PCR+ encephalopathy and control groups with regard to HHV-6 and CD68 positive cells mirrors the results described in the previous results section." (PMID 28072884, 2017).
epithelioid mesothelioma (2 papers, 2014 to 2017). "In summary, our data demonstrate for the first time an association of survival with high CD4+, low FOXP3+, high CD20+, low NP57+ and low CD68+ counts in epithelioid mesothelioma, treated with palliative intent." (PMID 28817839, 2017). "In conclusion, CD163/CD68 ratio was found to be a prognostic marker in a limited number of epithelioid mesothelioma patients, but not a predictive marker for outcome after surgery." (PMID 25192022, 2014). "Our data revealed that the CD163/CD68 ratio is a potential prognostic marker in epithelioid mesothelioma patients independent of treatment but cannot be used as a predictive marker for outcome after surgery." (PMID 25192022, 2014).
fibrosarcoma (2 papers, 2020 to 2021). A malignant mesenchymal fibroblastic neoplasm affecting the soft tissue and bone. "CD68 has a wide range of expression and poor specificity, and can be used for the diagnosis of fibrosarcoma." (PMID 32974176, 2020).
frontotemporal dementia (2 papers, 2018 to 2022). Frontotemporal dementia (FTD) comprises a group of neurodegenerative disorders, characterized by progressive changes in behavior, executive dysfunction and language impairment, as a result of degeneration of the medial prefrontal and frontoinsular cortices. "Patients suffering from frontotemporal dementia (FTD) who have P301S mutation depict CD68 positive microglial cells that are activated around neurons that pertain hyperphosphorylated Tau." (PMID 30149687, 2018). "The preliminary data obtained from our laboratory clearly indicate the co-localization between CD206+ and CD68+ microglia with Nogo-A, respectively, in various neurological diseases such as AD, frontotemporal dementia (FTD) and MS." (PMID 36497029, 2022).
gonarthrosis (2 papers, 2021 to 2024). "We found that the level of CD68+ was increased in the synovial tissue of patients with PsA compared with the synovial tissue of patients with activated gonarthrosis." (PMID 39629578, 2024). "The expression of CD68+ positive cells was significantly higher in patients with PsA compared to those with activated gonarthrosis (p < 0.001)." (PMID 39629578, 2024). "We also found that in our samples of patients with gonarthrosis, there was a lack of expression of CD68+ cells in their synovial tissue, with the difference between the two groups being significant (p < 0.001)." (PMID 39629578, 2024). "In the synovial tissue of patients with gonarthrosis, there was a lack of positive expression of CD68+ cells (n = 100, 0%), and the difference between the two groups was significant (p <0.001)." (PMID 39629578, 2024).
heart failure (2 papers, 2021 to 2024). Inability of the heart to pump blood at an adequate rate to meet tissue metabolic requirements. "POSTN(+)CD68(+)COL1A1(+) cells were clearly observed in human tissues from patients with heart failure, indicating the presence of the MMT in human hearts." (PMID 39261656, 2024). "WBC, suPAR, infiltrative CD68+, CD4+, CD54+, and HLA-DR+ cells did not correlate with any of the heart failure severity parameters." (PMID 34685378, 2021).
hemorrhage (2 papers, 2015 to 2020). Loss of blood from the vascular compartment to the exterior or into nonvascular body space as a result of rupture or severance of the blood vessels. "Our finding substantiate that 64Cu-DOTATATE is correlated primarily with CD163 positive macrophages (CD163+) and only weaker with CD68 positive macrophages (CD68+) making 64Cu-DOTATATE uptake a predictor of (hemorrhage-associated macrophages) macrophage activity." (PMID 25977567, 2015).
hepatopulmonary syndrome (2 papers, 2012 to 2019). Hepatopulmonary syndrome (HPS) is a lung disease characterized by widening of arteries and veins (dilatation) in the lungs in people who have chronic liver disease. "CD68+ macrophages generated vasodilatory, angiogenic and proliferative growth factors in the hepatopulmonary syndrome in rats." (PMID 23110041, 2012). "Activated CD68+ macrophages accumulated in the pulmonary arteries of hepatopulmonary syndrome and macrophage depletion by intravenous injections of either gadolinium chloride or liposomal clodronate prevented and reversed hepatopulmonary syndrome." (PMID 31815093, 2019).
HIV encephalitis (2 papers, 2015 to 2020). "The adjacent brain showed classic features of HIV encephalitis with perivascular, CD68 and p24-positive multinucleated giant cells." (PMID 26328586, 2015). "This immunophenotype is most consistent with a histiocytic infiltrate, and in the setting of pathognomonic HIV encephalitis with CD68-positive multinucleated histiocytes, would favor a reactive process due to HIV infection." (PMID 26328586, 2015). "In HIV encephalitis, many TSPO-positive cells were co-stained with CD68, a macrophage-lineage marker." (PMID 31963507, 2020).
infertile (2 papers, 2020 to 2025). "However, dysfunction or overactivation of T cells (CD3, CD4, CD8), B cells (CD20), and macrophages (CD68) can disrupt endometrial immune homeostasis, triggering chronic inflammation and impairing embryo implantation, ultimately leading to infertility." (PMID 40375897, 2025).
inflammatory pseudotumor (2 papers, 2019 to 2025). "Positivity for CD45 and CD68 in the larger spindled cells points to an inflammatory pseudotumor subtype and co-expression of CD21, CD23, and CD35 were indicative of follicular dendritic differentiation." (PMID 31885993, 2019).